SIRT1 (sirtuin 1)
Diseases named in the same sentence as SIRT1 in open-access papers (continued):
Sharing a sentence is not in itself a finding about the gene and the disease.
Sepsis (continued). "In summary, taraxerone inhibited inflammatory damage and oxidative stress in sepsis-induced ALI mice by activating SIRT1." (PMID 39543653, 2024). "SIRT1 also reduces endoplasmic reticulum stress, mitochondrial dysfunction, and excessive ROS production in sepsis-induced ALI models by inhibiting oxidative stress." (PMID 39543653, 2024). "Further, it was found that lncRNA taurine upregulated gene 1 (TUG1) in EPC-EVs upregulated sirtuin 1 (SIRT1) to facilitate the polarization of M2 macrophages by competitively binding to miR-9-5p thereby ameliorating sepsis." (PMID 38840175, 2024). "Research has also revealed that SIRT6, SIRT1, and NF-κB collaborate in orchestrating the metabolic reprogramming of energy during the pathophysiological processes of sepsis." (PMID 39234245, 2024). "In a rodent model of sepsis-induced acute kidney injury, a reduction in the activities of SIRT1 and SIRT3 led to heightened acetylation levels of SOD2, accompanied by oxidative stress and mitochondrial impairment." (PMID 39234245, 2024). "Autophagy activation via the AMPK/SIRT1 signaling pathway has been shown to mitigate sepsis-induced renal injury." (PMID 39544947, 2024). "In this study, we first demonstrated that taraxerone activates SIRT1 both in vitro and in vivo, alleviating oxidative stress and the inflammatory response in the lungs of mice with sepsis-induced ALI." (PMID 39543653, 2024). "This suggests the scheme’s effectiveness in mitigating liver damage induced by sepsis through the further promotion of SIRT1 functionality." (PMID 38690282, 2024). "Sirt1 deficiency increases microvascular inflammation in obese mice with sepsis; however, SIRT1 expression is increased by resveratrol, and that of ICAM-1 is downregulated under resveratrol treatment in ob/ob mice." (PMID 39372420, 2024). "Previous research highlighted the regulatory role of SIRT1 in HMGB1 under various disease conditions, such as sepsis-associated acute kidney injury." (PMID 38034869, 2023). "In conclusion, SIRT1 mediated the protective effects of echinacoside in mice with sepsis-induced ALI." (PMID 38001778, 2023). "Tetrahydrocurcumin significantly increased the expression of SIRT1 and inhibited inflammation and oxidative stress, thereby preventing sepsis-induced acute kidney injury in a CLP mouse model." (PMID 37628912, 2023). "AICAR, an AMPK agonist, acts on PGC1α through activation of SIRT1 and reduces cardiac dysfunction in CLP models, while Compound C, an AMPK antagonist, enhances tissue damage associated with sepsis." (PMID 36820088, 2023). "For example, we recently reported the involvement of NAD+/SIRT1 in the modulation of HMGB1 during sepsis." (PMID 38057866, 2023). "Vachharajani and colleagues used a highly specific sirtuin 1 inhibitor, EX-527, in mice 24 h after the onset of sepsis." (PMID 36831207, 2023). "In studies of mice, Labiner found that a knockout of SIRT1 in mice exacerbated renal mitochondrial dysfunction and increased inflammation and mortality in sepsis." (PMID 36980927, 2023). "These enzymes, in particular sirtuin 1 (SIRT1), are responsible for sensing the metabolic reprogramming of immune cells in the initial phase of sepsis." (PMID 37109229, 2023). "In a mouse model of sepsis, melatonin can alleviate blood-brain barrier dysfunction and brain edema through the SIRT-1 pathway." (PMID 37205094, 2023). "BMSCs protected rats against sepsis-induced AKI by promoting mitophagy via upregulating SIRT1/Parkin." (PMID 37215112, 2023). "Blocking SIRT1 in sepsis mice during adaptation restores immunity, rebalances mitochondrial bioenergy, and improves survival." (PMID 37371959, 2023). "SIRT1 controls the expression of multiple transcriptional factors, such as PGC-1α, which are closely associated with sepsis-induced cardiac dysfunction." (PMID 37246430, 2023). "The SIRT1 inhibitor EX527 reverses the protective function of nicotinamide ribosomes on sepsis-triggered cardiac injury." (PMID 37246430, 2023).
Sepsis (continued). "For example, a recent study revealed that METTL3 mediates the m6A methylation of SIRT1 mRNA, which suppresses SIRT1 protein expression and autophagic flux and eventually results in sepsis-induced acute lung injury." (PMID 38112620, 2023). "Polydatin protected against mitochondrial dysfunction in sepsis-induced-AKI by activating mitophagy via upregulating SIRT1." (PMID 37215112, 2023). "Previous study showed that SIRT1 phosphorylation by administration of dexmedetomidine significantly reduce sepsis-induced lung injury in rat model." (PMID 36717779, 2023). "Numerous studies have substantiated that activating SIRT1 can mitigate the inflammatory response induced by sepsis and confer protection against acute kidney injury." (PMID 38259279, 2023). "SIRT1 can activate several transcription factors, such as PGC-1α, resulting in enhanced mitochondrial biogenesis under energy deficiency during sepsis." (PMID 36064371, 2022). "This study suggests that, in the S1 segment, SIRT1 acts as a protective mechanism against sepsis-induced AKI." (PMID 35277012, 2022). "Differential analysis of NOS3, MMP2, HSP90AA1, and SIRT1 in the sepsis kidney injury-control group (SKi-C) showed that the p-value were all <0.05, indicating differential expression." (PMID 36406124, 2022). "In the endotoxin tolerance process of sepsis, SIRT1 accumulates in the promoters of IL-1β and TNF-α and NAD+ levels increase, which enhances H3K16 deacetylation." (PMID 35359990, 2022). "Treatment with exosomes from mesenchymal stem cells in adipose tissue activated SIRT1 and decreased the state of inflammation, apoptosis rate, and microcirculation disorders in mice with sepsis-induced AKI." (PMID 35277012, 2022). "Activation of SIRT1 has beneficial effect in the initial (proinflammatory) phase, characterized by a cytokine storm, overproduction of reactive oxygen species (ROS), and metabolic shift, while SIRT1 expression should be inhibited in the later stages of sepsis." (PMID 36139711, 2022). "Syringaresinol (SYR) improved cardiac function and alleviated myocardial injury in sepsis-induced cardiac dysfunction mouse via the estrogen receptor (ER)/SIRT1/NLRP3/GSDMD pathway." (PMID 35509275, 2022). "The results of renal ROS also indicated that the silence of the SIRT1/Nrf2 axis reversed the protective impact of irisin on lessening lipid ROS accumulation stimulated by sepsis." (PMID 35370723, 2022). "Mice with renal injury and sepsis showed decreased SIRT-1/3 activity as well as increased ac-SOD2 levels, oxidative stress, and mitochondrial damage." (PMID 35222035, 2022). "It has been found that pyroptosis participated in the pathogenesis of sepsis-induced myocardial injury which was associated with the XIST/miR-150-5p/c-Fos axis and ER/SIRT1/NLRP3/GSDMD pathway." (PMID 35509275, 2022). "The analysis showed that NOS3, SIRT1, HSP90AA1, MMP9, MMP2, PTPRC, and TLR2 were associated with multiple organ damage in sepsis." (PMID 36406124, 2022). "Several works have indeed established the interaction between gut microbe Lactobacillus and SIRT1 activity in different diseases such as aging, colitis, sepsis, and anxiety." (PMID 36555725, 2022). "Although the function and molecular mechanisms by which SIRT1 regulates the inflammatory response during sepsis have been extensively reviewed elsewhere, our focus is on the role of SIRT1 in the regulation of host defenses against infection." (PMID 36139497, 2022). "SIRT1 attenuated sepsis-induced AKI via the deacetylation of Beclin1 at lysine 430 and lysine 437, associated with autophagy." (PMID 35359990, 2022). "SIRT1 can regulate immunometabolic polarity during the hyper-inflammatory and hypo-inflammatory phases of sepsis." (PMID 35359990, 2022). "Taken together, SIRT1 is presumed to be a promising novel target for treating sepsis, but further studies are necessary to evaluate systemic immune homeostasis." (PMID 35359990, 2022).
Sepsis (continued). "aloin reduces HMGB1 release and sepsis-related mortality by activating SIRT1 and PI3K/Nrf2/HO-1 signals." (PMID 35720285, 2022). "Prior studies and our previous research showed that SIRT1 was versatile in sepsis treatment and that drug-activated SIRT1 exerted multiple beneficial effects against sepsis." (PMID 33637691, 2021). "Mechanically, melatonin attenuated sepsis-induced small-intestine injury through SIRT1/3 activation." (PMID 33790896, 2021). "For instance, activation of the AMPK/SIRT1 signaling pathway was shown to attenuate lung inflammation and apoptosis in a rat model of sepsis and ameliorated LPS-induced impairment of alveolar epithelial barrier function." (PMID 33693011, 2021). "Activation of Sirt-1 by agents including resveratrol improved sepsis because Sirt-1 reduced inflammatory response and modulated redox balance." (PMID 34493741, 2021). "The specific molecules related to SIRT1-mediated macrophage polarization in sepsis warrants further investigation." (PMID 34743197, 2021). "We discovered that OIP5-AS1 and Sirtuin1 (SIRT1) were markedly down-regulated in sepsis models elicited by CLP or LPS, while miR-128-3p experienced a dramatic up-regulation." (PMID 34592882, 2021). "AE prominently downregulated CXCL-1, CXCL-8, IL-6, TNF-α, Glu1, and HMGB1 mRNA expression but activated IL-1RN, IL-10, Sirt-1, and Nrf-2 mRNA expression in the lung during sepsis." (PMID 34493741, 2021). "It has been revealed that melatonin treatment elevates the expression and activity of SIRT1 in various animal/cell sepsis models, and alleviates sepsis-induced brain and liver injury, as well as cardiac dysfunction." (PMID 33790896, 2021). "Theacetylation-dependent interaction between HMGB1 and SIRT1 is critical for LPS-induced lethality in an experimental model of sepsis." (PMID 33925132, 2021). "It was previously reported that SIRT1-modulated HMGB1 deacetylation inhibited acute kidney injury incurred by sepsis." (PMID 34906140, 2021). "To conclude, the current study gives evidence for the contribution of TUG1 to macrophage polarization and its anti-inflammatory potency by blocking miR-9-5p-induced silencing of SIRT1 in sepsis." (PMID 34743197, 2021). "SIRT1 can hinder the acetylation of NICD to restrain activation of Notch signaling to subsequently alleviate sepsis." (PMID 34743197, 2021). "All in all, OIP5-AS1 overexpression enhanced sepsis-induced ALI by modulating the miR-128-3p/SIRT1 pathway, which helps create new insights into sepsis treatment." (PMID 34592882, 2021). "During sepsis, sirtuin 1 (SIRT1) rapidly accumulates in the TNF-α and IL-1β gene promoters, deacetylating H4K16 and blocking NF-kB-dependent transcription." (PMID 34322502, 2021). "This was consistent with a previous study that indicated that DEX increased the levels of p-AMPK and p-SIRT1 significantly in lung tissues of rats in a model of sepsis-induced lung injury." (PMID 33981237, 2021). "Meanwhile, SIRT1 suppresses acute lung inflammation during sepsis by controlling the activation of inflammatory pathway, so it is highly possible that MAR1 reduce the inflammatory response by activating SIRT1 in sepsis." (PMID 33557833, 2021). "Meanwhile, it can also enhance the intervention effect of the drug dexamethasone on sepsis in mice by regulating the expression of SIRT1." (PMID 34721636, 2021). "Recent reports from our group showed that EX-527, a SIRT1 inhibitor, reverses hypo-inflammation in sepsis mice and improves survival." (PMID 35052507, 2021).
Sepsis (continued). "In contrast to NGAL, mnSOD and HIF1α, the expression of SIRT1, involved in inhibiting oxidative stress and the suppression of biogenesis and mitophagy, was downregulated in sepsis-AKI patients." (PMID 33494815, 2021). "Sirt1 regulates many actions in sepsis-induced cardiomyopathy, such as alleviating inflammation, inhibiting apoptosis, depressing oxidative damage, and repressing endoplasmic reticulum stress." (PMID 33869205, 2021). "Studies have confirmed that DEX attenuates sepsis induced by acute lung injury through the SIRT1-dependent AMPK pathway." (PMID 33981237, 2021). "Our study confirmed melatonin’s role in SIRT1 protein/activity upregulation in sepsis-challenged small-intestine tissue." (PMID 33790896, 2021). "In the present study, we have unveiled that in rats and NR8383 and RLE-6TN cells mediated by sepsis, SIRT1 relative expression shows a decrease, and the relative expression of p-NF-κB and iNOS is increased." (PMID 34592882, 2021). "Our study reveals that melatonin alleviates sepsis-induced small-intestine injury by upregulating SIRT1 and SIRT3." (PMID 33790896, 2021). "Increased expression of miR-133a in sepsis patients and rodent sepsis aggravates an inflammatory response by targeting SIRT1." (PMID 35052507, 2021). "As an example, in a ligation and puncture murine model of sepsis, SIRT1 attenuates sepsis-induced lung inflammatory injury via repressing the inflammasome activation pathway and decreasing the production of proinflammatory mediators." (PMID 33263643, 2020). "This study aimed to investigate the value of sirtuin 1 (SIRT1) in differentiating sepsis patients from healthy controls (HCs), and its correlation with inflammation, disease severity, as well as prognosis in sepsis patients." (PMID 33263643, 2020). "The mean level of SIRT1 was 1.947±0.983 ng/mL in HCs and 0.587±0.365 ng/mL in sepsis patients, and comparison analysis showed that SIRT1 was significantly lower in sepsis patients compared with HCs (P<0.001)." (PMID 33263643, 2020). "Herein, the aim of the present study was to investigate the potential of SIRT1 as a biomarker for disease management and prognosis prediction in sepsis patients." (PMID 33263643, 2020). "The present study was the first to evaluate the clinical value of SIRT1 for the progression and prognosis of sepsis, however, several limitations should be noted when interpreting the findings." (PMID 33263643, 2020). "As for SIRT1, it is a single index measurement, which allowed rapid detection for indicating the prognosis in sepsis patients." (PMID 33263643, 2020). "It is worth nothing that Sirt1 was recently reported that playing critical role to preventing autoimmunity and participate in sepsis progress." (PMID 32978453, 2020). "SIRT1 was decreased in sepsis patients compared with HCs, and the receiver operating characteristic curve (ROC) showed that SIRT1 distinguished sepsis patients from HCs (area under the curve (AUC): 0.901; 95% confidence interval (CI): 0.868-0.934)." (PMID 33263643, 2020). "We found that melatonin attenuated sepsis induced lung injury, improved survival rate, enhanced alveolar fluid clearance, improved SIRT1 activity, increased protein expressions of SIRT1 and ENaC, and activated SGK1/Nedd4-2 pathway." (PMID 33362546, 2020). "SIRT1 is the most extensively studied sirtuin, and it is reported to have a protective effect in inflammation-related multiple organ dysfunction of sepsis." (PMID 33263643, 2020). "The results of this study also suggest that melatonin attenuates sepsis-induced AFC reduction through up regulating ENaC expression via activation of SIRT1/SGK1/Nedd4-2 signaling pathway." (PMID 33362546, 2020). "We also found that melatonin significantly alleviated lung injury and reduced the release of inflammatory mediators in a SIRT1 dependent manner during sepsis." (PMID 33362546, 2020).
Sepsis (continued). "Our results showed that ginsenoside Rg1 treatment effectively relieved sepsis-induced lung injury in vitro and in vivo, mainly via upregulating SIRT1 to relieve ER stress and inflammation." (PMID 30918470, 2019). "In other disease model where SIRT1 has gained prominent improvement such as sepsis-induced liver injury in particular, such improving effects were dependent on SIRT1 pathway activation." (PMID 30918470, 2019). "Resveratrol can upregulate SIRT1 to inhibit inflammation and hence attenuated severe liver injury following sepsis." (PMID 31354914, 2019). "In summary, our study found that ginsenoside Rg1 attenuated ER stress via upregulating SIRT1 to ameliorate sepsis-induced acute lung injuries both in LPS-induced pulmonary epithelial cells and CLP sepsis mouse models." (PMID 30918470, 2019). "In summary, our results suggest that Cx43 inhibition suppresses ROS transfer and inactivates the JNK1/Sirt1/FoxO3a signaling pathway to protect against sepsis-induced intestinal injury." (PMID 30948926, 2019). "miR-181a-5p down-regulation inhibited inflammatory response in vitro and in vivo through repressing NF-κB signaling pathway by targeting SIRT1, indicating the anti-inflammatory effect of miR-181a-5p inhibitor in sepsis." (PMID 31844680, 2019). "The expression of miR-181a-5p/SIRT1 in patients with sepsis, and the relationship between the expression of miR-181a-5p/SIRT1 and the clinical features of patients with sepsis are necessary to be explored." (PMID 31844680, 2019). "Although the JNK1/Sirt1/FoxO3a signaling pathway was activated by sepsis, the changes of the key points were different." (PMID 30948926, 2019). "We confirmed that miR-181a-5p directly targeted SIRT1 and it negatively regulated the expression of SIRT1 in RAW 264.7 macrophages, thus revealing a possible mechanism of SIRT1 with inflammation response in sepsis." (PMID 31844680, 2019). "Inhibition of SIRT1 in vivo (using a SIRT1-specific inhibitor, EX-527) increased complications of sepsis at 12 h despite conferring dramatic protection at 24 h." (PMID 31354630, 2019). "For example, a recent study found that SIRT1 regulates inflammatory response of macrophages in sepsis, perhaps by mediating a long-coding RNA molecule." (PMID 30918470, 2019). "Then, we also determined the effects of miR-181a-5p inhibitor or SIRT1-siRNA in mice with sepsis induced by LPS administration." (PMID 31844680, 2019). "In conclusion, this study shows for the first time in a lethal model of sepsis in mice that a regulatory node controlled by a selective SIRT1 inhibitor known to improved sepsis survival coordinates innate and adaptive immune cell polarity." (PMID 30069485, 2018). "Blocking SIRT1 during the immune tolerance sepsis phenotype in mice restores immunometabolic and energy homeostasis, resolves systemic inflammation and markedly improves survival." (PMID 29593712, 2018). "Inhibiting glycolysis by 2-deoxyglucose, a hexokinase-2 inhibitor, prevents cardiac dysfunction and glycolysis along with increased SIRT1/SIRT3 levels during early sepsis." (PMID 30216989, 2018). "In this study, we did not design experiments to explore the relationship between LXA4 and SIRT1 in brain dysfunction induced by sepsis, but it does have the potential to become a novel point in our future studies." (PMID 30186119, 2018). "Our previous study found that SIRT1 activity and protein expression were greatly reduced following sepsis, accompanied by hyperacetylated manganese superoxide dismutase (SOD2)." (PMID 30533222, 2018).